KEAP1 (kelch like ECH associated protein 1)
Diseases named in the same sentence as KEAP1 in open-access papers (continued):
Sharing a sentence is not in itself a finding about the gene and the disease.
lung carcinoma (continued). "Ferroptosis induced by pharmacological inhibition of the CoQ-FSP1 axis makes KEAP1 deficient lung cancer cells or patient-derived xenograft tumors sensitive to radiation." (PMID 37714846, 2023). "KEAP1 is frequently mutated or inactivated in lung cancers, while KEAP1 mutant lung cancers are resistant to most therapies including radiotherapy." (PMID 37714846, 2023). "Together, our data reveal that KEAP1 deficiency or mutation in lung cancer cells promotes ferroptosis resistance to class 2 FINs but does not affect ferroptosis sensitivity to the class 3 FIN." (PMID 35459868, 2022). "In a retrospective study of 9243 patients (4647 with lung cancer), KEAP1/NFE2L2 mutations were associated with higher tumor mutational burden and higher programmed death-ligand 1 expression." (PMID 35371318, 2022). "In an analysis of 99 KEAP1-mutated lung cancer patients using an online database, patients with KEAP1 mutations had a shorter OS after ICI treatment." (PMID 35407463, 2022). "Keap1 loss and Nrf2 activation promotes lung cancer metastasis by accumulating BTB domain and CNC homolog 1 (Bach1), which has been reported to stimulate transcription of HK2 triggering glycolysis-induced metastasis." (PMID 36419136, 2022). "In the lung cancer cells, Keap1 mutations showed more resistance to etoposide and carboplatin than to Keap1 wild-type cells." (PMID 35945195, 2022). "Activation of the Nuclear factor-erythroid factor 2-related factor 2 (NRF2) pathway through gain-of-function mutations or loss-of-function of its suppressor Kelch-like ECH-associated protein 1 (KEAP1) is frequent in lung cancer." (PMID 35626147, 2022). "Here, the authors show that KEAP1 mutations in lung cancer cells leads to FSP1 upregulation through NRF2, resulting in ferroptosis resistance and radioresistance." (PMID 35459868, 2022). "Sirpiglenastat also demonstrated promising effects in a glutamine-dependent KRAS-mutant lung cancer model that carries KEAP1 mutations and reduced KEAP1-mutant tumor growth in both murine and patient-derived lung and squamous tumor models." (PMID 34981784, 2022). "Two laboratories independently discovered somatic mutations in the KEAP1 gene in lung cancer cells that disrupt the protein–protein interaction of KEAP1-NRF2, leading to the constitutive activation of NRF2." (PMID 36230622, 2022). "Of note, loss of tumor suppressor KEAP1 in lung cancers leads to glucose dependency through upregulating cystine metabolism-mediated NADPH consumption, suggesting an emerged metabolic vulnerability due to genetic alteration of such gene." (PMID 35178349, 2022). "The continuous activation of Nrf2 in lung cancer cells is generally due to the mutation of the Keap1/NFE2L2 gene, thus resulting in drug resistance and significant invasiveness." (PMID 35721205, 2022). "Targeting the CoQ-FSP1 axis renders KEAP1 deficient or mutation lung cancer cells sensitive to radiotherapy-induced ferroptosis." (PMID 35882850, 2022). "Activation of the NRF2 pathway through gain-of-function mutations or loss-of-function of its suppressor KEAP1 is a frequent finding in lung cancer." (PMID 35626147, 2022). "Dietary restriction to exogenous non-essential amino acids, including Asn, also hindered the growth of lung cancers that harbored Kelch-like ECH-associated protein 1 (KEAP1)/NRF2 mutations in vivo, wherein the oxidative stress response was activated." (PMID 36090030, 2022). "To understand the role and mechanisms of KEAP1 in regulating ferroptosis, we examined the effect of KEAP1 deficiency on ferroptosis sensitivity to different classes of FINs in lung cancer cells." (PMID 35459868, 2022).
lung carcinoma (continued). "We further show that pharmacological inhibition of the CoQ-FSP1 axis sensitizes KEAP1 deficient lung cancer cells or patient-derived xenograft tumors to radiation through inducing ferroptosis." (PMID 35459868, 2022). "This treatment led to an increase in ROS and suppressed cellular proliferation in KEAP1 mutated lung cancer cells." (PMID 35053572, 2022). "In a recent study, it was reported the Keap1-Nrf2 double mutations in lung cancer leads to poor outcome and severe therapeutic resistance in radiation therapy." (PMID 35945195, 2022). "We further propose that pharmacological targeting of CoQ-FSP1 signaling can be exploited to overcome KEAP1 deficiency-induced radioresistance and to treat KEAP1 mutant lung cancers." (PMID 35459868, 2022). "Aldo-keto-reductase 1C (AKR1C) family members were identified as NRF2-regulated ferroptosis-protective genes, and their increased expression underlies the progression of lung cancers with concurrent KEAP1 and STK11 mutations." (PMID 36282248, 2022). "Keap1 mutation or deficiency in lung cancer cells upregulates FSP1 expression through Nrf2, leading to ferroptosis- and radiation-resistance." (PMID 36105219, 2022). "Collectively, these data suggest that FSP1 inactivation promotes radiosensitization in KEAP1 deficient or mutant lung cancer cells mainly through inducing ferroptosis." (PMID 35459868, 2022). "STK11 and KEAP1 comutations have been associated with worse outcomes in patients with KRAS-mutant lung cancer treated with an ICI." (PMID 36426286, 2022). "About 30% of human lung cancers have Keap1 or nfe2l2 mutations, resulting in the stability of nfe2l2 gene product NRF2, which controls the oxidation balance." (PMID 35770119, 2022). "A most recent work reveals that FSP1 is upregulated through NRF2-mediated transcription in KEAP1 mutant or deficient lung cancer cells." (PMID 35882850, 2022). "We and others recently revealed an important role of ferroptosis in RT-induced cell death, prompting us to examine the potential role of FSP1 in mediating radioresistance in KEAP1 deficient lung cancer cells." (PMID 35459868, 2022). "Together, these data suggest that FSP1 is an NRF2 transcriptional target and that KEAP1 deficiency in lung cancer cells leads to FSP1 upregulation through NRF2, resulting in ferroptosis resistance." (PMID 35459868, 2022). "Conversely, the mRNA levels for pirin decreased by 90% upon knockout of Nrf2 in the human lung cancer cell line A549, which has constitutively high levels of Nrf2 due to a mutation in Keap1 and hypermethylation of its promoter." (PMID 35204145, 2022). "In this work, we identify FSP1 as an NRF2 transcriptional target and reveal that KEAP1 mutation or deficiency in lung cancer cells upregulates FSP1 expression through NRF2, leading to ferroptosis- and radiation- resistance." (PMID 35459868, 2022). "We made similar observations in lung cancer patient-derived xenografts (PDXs) with KEAP1 mutation (TC494)." (PMID 35459868, 2022). "Kelch‐like ECH‐associated protein 1 (KEAP1) mutation is one of the most common lung cancer mutations, and its mutant frequency has been over 20% in lung adenocarcinoma (LUAD)." (PMID 34617407, 2021). "Another regulatory mechanism of BACH1 expression includes mutation in either Keap1 or Nfe2l2 that comprises about 30% of human lung cancer." (PMID 33809182, 2021). "Collectively, co-mutations of LKB1 and/or KEAP1 with KRAS in lung cancer are associated with KRAS independency through a rewiring of metabolic processes." (PMID 34680229, 2021). "KEAP1 is frequently mutated in lung cancer, and KEAP1-mutant lung cancer exhibits NRF2 hyperactivation and aberrant expression of SLC7A11." (PMID 33000412, 2021). "In some tumors, such as lung cancer, Nrf2 is found to be constitutively expressed primarily for mutations affecting the KEAP-1 suppressor." (PMID 33799965, 2021).
lung carcinoma (continued). "While the loss of Keap1 fosters KRAS (a proto-oncogene GTPase)-mediated lung cancer, previous studies proved Nrf2-driven protection in vivo against carcinogen-induced lung cancer." (PMID 33466626, 2021). "The treatment of lung cancer was gradually developing, but the patients with KEAP1/NFE2L2/CUL3 mutations were in a dilemma." (PMID 34617407, 2021). "In KEAP1-deficient lung cancer, RSPO3, the ligand that activates Wnt signaling, is upregulated due to the Keap1 deficiency and, along with its receptor LGR4, mediates cell migration and metastasis in an IQGAP1-dependent manner." (PMID 34439095, 2021). "Due to somatic loss-of-function mutations in Keap1, Nrf2 is typically activated in lung cancer, particularly in adenocarcinomas." (PMID 33670717, 2021). "In lung cancer, Nestin was reportedly capable of protecting Nrf2 from kelch-like ECH-associated protein 1 (Keap1)-modulated degradation and was able to increase the expression levels of antioxidant enzymes." (PMID 34837964, 2021). "Mutated Keap1 was reported in several cancers, viz., lung cancer, HCC, endometrial cancer, bladder cancer, colon cancer, head and neck cancer, and esophagogastric cancer." (PMID 33466626, 2021). "In another scenario, somatic mutations of KEAP1 identified in lung cancer patients promote tumorigenesis." (PMID 34575683, 2021). "Particularly in lung cancer, inactivating somatic mutations on KEAP-1 cysteine residues have been observed, resulting in constitutive activation of Nrf2." (PMID 33799965, 2021). "Either antioxidant treatment-induced BACH1 or Keap1 loss-induced Bach1 promoted lung cancer metastasis." (PMID 33809182, 2021). "Thirty percent of human lung cancers develop mutations in either KEAP1 or NFE2I2, which promote metastasis in LUAD by leading to the stabilization of NRF2, the NFE2I2 gene product." (PMID 33658393, 2021). "Regarding other lung cancer sub-types, Keap1 mutations have been found in an LCC tumor in mice, in SCLC (NCI-H1184, a human cell line) and in some pulmonary large-cell neuroendocrine carcinoma (LCNECs), although at a lower frequency than in LUSC or LUAD." (PMID 34440648, 2021). "Further study showed that ML385 substantially enhances paclitaxel, doxorubicin, or carboplatin cytotoxicity against lung cancer cells with Keap1 mutation." (PMID 33324555, 2020). "The inactivation of KEAP1 in KRAS mutations is related to the inhibition of glutaminase in lung cancer." (PMID 32206449, 2020). "These preliminary datas suggest that ML385 inhibits the proliferation of lung cancer cells with KEAP1 mutations by blocking the KEAP1/NRF2 antioxidant stress response pathway." (PMID 32576270, 2020). "Lignito’s results showed that loss of Keap1 or Fbxo22 induces metastasis in a Bach1-dependent manner and causes a notable increase in the metastatic phenotype in mouse models of lung cancers." (PMID 32629428, 2020). "In the present study, we found that the loss-of-function mutation inKEAP1 promotes the development of lung cancer mediated by activation of the KEAP1/NRF2 pathway." (PMID 32576270, 2020). "Collectively, these findings demonstrate that KEAP1 loss can enhance the ability of lung cancer cells to resist oxidative stress." (PMID 32576270, 2020). "By analyzing the clinical datasets, we found that KEAP1 mutations showed significant positive correlation with SOX9 expression in the TCGA lung cancer cohort." (PMID 33173725, 2020). "The somatic nonsynonymous mutations in KEAP1 derived from patients with lung cancer likely promote tumorigenesis via activation of the KEAP1/NRF2 antioxidant stress response pathway." (PMID 32576270, 2020). "While the mutational status of KEAP1 is one of the most critical biomarkers for molecular classification and general survival time of the patients, high SOX9 expression appeared to confer poor outcome in KEAP1‐mutated lung cancer patients." (PMID 33173725, 2020).
lung carcinoma (continued). "In KrasG12D mutated lung cancer, Keap1 mutation leads to high Nrf2 levels thereby positively regulating TALDO1 levels to promote oncogenesis and cancer development via PPP levels." (PMID 33324555, 2020). "Our study found that UGTA1A, NQO1 and GSTA gene expression levels in lung cancer tissues carrying KEAP1/NRF2 gene mutations significantly increased in comparison with those in lung cancer tissues without KEAP1/NRF2 gene mutations." (PMID 32629428, 2020). "These lung cancer cell lines that carry loss-of-function mutations in KEAP1, were losing the ability to mediate NRF2 degradation." (PMID 32576270, 2020). "KEAP1 promoter methylation was first reported in lung cancer, but similar observations have been linked to poor prognosis in glioma, breast cancer, non-small cell lung carcinoma, colorectal cancer, clear renal cell carcinoma, and pancreatic cancer." (PMID 32938017, 2020). "Altogether, the data obtained from the KEAP1-mutated lung adenocarcinoma followed the previous reports of Genome-wide DNA methylation patterns in lung cancer." (PMID 32327612, 2020). "The loss-of-function mutation of KEAP1 promoted the tumorigenesis of Kras- and Pten-driven lung cancer cell lines in mice." (PMID 32576270, 2020). "Studies had shown that activation of the Nrf2 protein and its regulatory signaling pathways caused by KEAP1 mutations is conducive to the survival of lung cancer cells and resistance to chemotherapy drugs." (PMID 32445554, 2020). "Loss-of-function mutations of Keap1 and gain-of-function mutations of Nrf2 have been observed in lung cancer." (PMID 33324555, 2020). "More recently, the data have also shown that loss of function of KEAP1 promotes KRAS-driven lung cancer and results in the dependence on glutaminolysis." (PMID 32576270, 2020). "Loss-of-function mutations in Keap1 were found in human lung carcinoma, NSCLC, gallbladder, ovarian, and liver cancers, whereas gain-of-function mutations in Nrf2 were found in lung, head and neck, and esophageal carcinoma." (PMID 31632280, 2019). "The high frequency of KEAP1 mutations has been considered as an important molecular event in lung cancer progressions." (PMID 31839815, 2019). "We confirmed that K‐563 inhibited the Keap1/Nrf2 pathway in Keap1‐mutated human lung cancer A549 cells." (PMID 30735010, 2019). "In preclinical models of KEAP1 mutated lung cancer cells, it was observed that ML385 plus carboplatin enhances the efficacy of anti-tumor activity of chemotherapic compounds." (PMID 31126053, 2019). "The mutational status of Keap1 and of Nrf2 have been directly connected to the success of localized radiotherapy in lung cancer, underscoring the crucial role of this E3 ubiquitin ligase-substrate axis in the cellular response to IR." (PMID 31632280, 2019). "NRF2 is frequently upregulated in lung cancer as a consequence of somatic mutations in KEAP1, NFE2L2, or CUL3, and associates with increased cell proliferation and resistance to anticancer drugs." (PMID 29102676, 2018). "The lack of mutations with high functional impact does not mitigate the importance of such missense mutations in protein function, as in the case of KEAP1 in lung cancer." (PMID 30662871, 2018). "To that end, we overexpressed either WDR23 isoform 1 or WDR23 isoform 2 in A549 lung carcinoma cells, where loss of KEAP1 results in NRF2 nuclear accumulation." (PMID 28453520, 2017). "Keap1 insertion and deletion mutations were found in 10 of 54 NSCLC patients, 6 of 12 cells line and a high incidence of Keap1 somatic mutations was also found in 65 Japanese patients with lung cancer." (PMID 28402268, 2017).
lung carcinoma (continued). "This certainly seems to be true of NRF2 activation in many types of cancer including lung cancer, where advanced disease is actually associated with the accumulation of genetic alterations in KEAP1 and NF2EL2 that promote constitutive activation." (PMID 28423681, 2017). "In all cases, this confirmed responsiveness to NFE2L2 siRNA silencing in A549, as well as one additional lung cancer cell line, H838, which similarly harbours a loss-of-function mutation in KEAP1." (PMID 28959951, 2016). "The R483H somatic mutation in KEAP1 has been reported in lung cancer tissue with elevated levels of NRF2 expression." (PMID 27703446, 2016). "Research has verified that somatic mutations of Keap1 or Nrf2 result in a gain of function of Nrf2 in both lung cancer patients and lung cancer cell lines." (PMID 27347930, 2016). "This study identified mutations in the Kelch/DGR domain of KEAP1 in lung cancer cell lines as well as lung cancer tissue samples and demonstrated that these mutant KEAP1 proteins lost their NRF2 repressive function, which resulted in NRF2 accumulation." (PMID 26682001, 2016). "The use of a comprehensive cancer panel including genes with recurrent mutations in lung cancer, such as KEAP1 and NF1, would certainly be more efficient to identify patients for whom ctDNA follow-up would be possible." (PMID 28027313, 2016). "To complement this observation we then used the A549 lung cancer cell line, which is known to harbor an inactivating mutation in KEAP1 gene." (PMID 27100653, 2016). "As an example of the utility of the resource, we show how canonical hotspot mutations in KEAP1 in lung cancer align with rare, and putatively functional, mutations in other Kelch_1-containing genes in melanoma." (PMID 26590264, 2016). "Mutations in KEAP1 have also been identified in human disease, most notably cancers of the lung, breast and gall bladder." (PMID 24641320, 2014). "In fact, mutations in the NRF2 and KEAP1 genes have been found in carcinomas of the lung, breast, liver, and stomach." (PMID 24040073, 2013). "Silencing of KEAP1 by hypermethylation has been described in lung cancer, and associated with stabilized NRF2 and increased expression of NRF2 target genes in colorectal cancer." (PMID 24138990, 2013). "Yamamoto and colleagues found a high incidence/frequency occurrence of loss of KEAP1 function in patients with lung cancer." (PMID 23577226, 2013). "Somatic mutations of NRF2 and KEAP1 discovered in lung cancer patients have determined the oncogenic potential of NRF2." (PMID 23936606, 2013). "KEAP1 somatic mutations were associated with its reduced protein levels in lung cancer tissues and cells." (PMID 23936606, 2013). "Further studies are required to confirm the mechanisms of Keap1 mutations to determine the sensitivity or resistance of therapy for lung cancer." (PMID 24137397, 2013). "The Keap1-Nrf2 signaling pathway is impaired in lung cancer, which is caused by mutations within functionally important domains of the KEAP1 or NRF2 gene." (PMID 22325485, 2012). "Downregulation of Keap1, consequent to gene mutations or loss of heterozygosity in the Keap1 locus, has been identified in lung cancer cell lines or cancer tissues and results in an upregulation of Nrf2 and in transactivation of its downstream genes." (PMID 23119185, 2012). "Sixty five Japanese patients with lung cancer showed a high incidence of Keap1 somatic mutations and in breast cancer a Keap1 (C23Y) mutation impaired its ability to repress Nrf2." (PMID 24281078, 2010). "It is also worth mentioning that LKB1 and NRF2 have often mutated genes (or KEAP1 in the case of the NRF2 pathway) in lung cancer that may act in synergy to adapt cells to oxidative stress, as already demonstrated." (PMID 39955067, 2025). "Targeting CNDP2 may be particularly beneficial for lung cancer patients that frequently carry mutations in the KEAP1 gene, as KEAP1 deficiency rendered cells more reliant on this cooperation." (PMID 40350469, 2025).